HRCT1 (histidine rich carboxyl terminus 1)
Synonyms: LGLL338; PRO537; UNQ338
Tractability: Antibody: UniProt predicts a signal peptide or a membrane-spanning region.
Gene: Protein-coding gene on chromosome 9 (35,906,202 to 35,907,136, forward strand). Ensembl gene ENSG00000196196.
Subcellular location: Membrane
Subcellular location (Human Protein Atlas): Nuclear membrane; Nuclear speckles; Nucleoplasm
Gene Ontology:
Cellular component: membrane
Genetic constraint (gnomAD): Missense variants: 185 observed, 148.44 expected, observed/expected ratio (o/e) 1.25, 90% interval 1.11 to 1.41. Synonymous variants: 76 observed, 63.94 expected, observed/expected ratio (o/e) 1.19, 90% interval 0.99 to 1.44.
Homologues: Orthologues: chimpanzee HRCT1 (99% identical), macaque HRCT1 (96% identical), dog HRCT1 (61% identical), pig HRCT1 (56% identical), mouse Hrct1 (52% identical), rat Hrct1 (51% identical).
Diseases named in the same sentence as HRCT1 in open-access papers:
HRCT1 is named in the same sentence as 9 diseases in open-access papers, as found by Europe PMC text mining. Sharing a sentence is not in itself a finding about the gene and the disease. The quoted sentences say what the papers report.
breast carcinoma (1 paper, 2021). "Of the remaining 12 genes, seven (A4GALT, C2ORF74, HRCT1, ZC4H2, ZNF512, ZNF655, and ZNF608) show similar relative expression profiles in large patient samples and other breast cancer cell lines thereby giving insight into predicted role of H3K4me3 mediated gene regulation via the miRNA-mRNA axis." (PMID 34261302, 2021).
narcolepsy (1 paper, 2022). A sleep disorder characterized by a tendency for excessive sleepiness during the day which occurs even after adequate sleep in the nighttime. "In the other two patients, the clinical picture and course of the disease in the long-term follow-up confirmed that these were solitary episodes of psychosis in the course of Hrct-1 deficient narcolepsy." (PMID 36672025, 2022).
HRCT1 also shares sentences with these, for which no sentence is quoted: tumor (2 papers); asthma (1); hypersomnia (1); multiple sclerosis (1); psychosis (1); rheumatoid arthritis (1); stomach adenocarcinoma (1).